CELF2 (CUGBP Elav-like family member 2)
Diseases named in the same sentence as CELF2 in open-access papers (continued):
Sharing a sentence is not in itself a finding about the gene and the disease.
leukemia (4 papers, 2021 to 2024). A malignant (clonal) hematologic disorder, involving hematopoietic stem cells and characterized by the presence of primitive or atypical myeloid or lymphoid cells in the bone marrow and the blood. "In the current study, we aimed to functionally dissect the role of CELF2 in leukemia using Celf2-deficient MLL-AF9 mouse models." (PMID 38514854, 2024). "Next, we evaluated the consequence of Celf2 loss in the maintenance of established AML leukemia." (PMID 38514854, 2024). "To determine how Celf2 deletion accelerates leukemia initiation, we serially transplanted the equal numbers of Celf2 KO + MA9 or MA9 leukemia cells into the recipient mice." (PMID 38514854, 2024). "The percentage of GFP+ leukemia cells and the degree of extramedullary infiltration were also increased in Celf2 KO + MA9 mice than that in MA9 mice, including in the spleen, liver and lung." (PMID 38514854, 2024). "Our data suggest that loss of Celf2 likely enhances the self-renewal and survival of Celf2 KO + MA9 cells through multiple molecular pathways that contribute to the MA9-induced leukemia." (PMID 38514854, 2024). "Consistent with more LSCs in the Celf2 KO + MA9 cell population, extreme limiting dilution transplantation assays demonstrated a marked increase in leukemia-initiating cell frequency in Celf2 KO + MA9 AML cells when compared with MA9 AML cells." (PMID 38514854, 2024). "To specifically define the downstream signals of CELF2 that are critical for leukemia progression, we analyzed integrated data from RIP-Seq and RNA-Seq to identify the target mRNA of CELF2." (PMID 38514854, 2024). "We found that the number and the percentage of c-Kit+Gr-1− leukemia cells were increased in BM of Celf2 KO + MA9 mice when compared with that of MA9 mice." (PMID 38514854, 2024). "Wright-Giemsa staining showed that the counts of abnormal leukemia cells was increased in PB and BM of Celf2 KO + MA9 mice when compared with that of MA9 mice." (PMID 38514854, 2024). "The percentage and absolute number of GFP+ leukemia cells were significantly increased in BM of Celf2 KO + MA9 mice, when compared with that of MA9 mice." (PMID 38514854, 2024). "In this model, Celf2 KO + MA9 mice showed more aggressive leukemia phenotypes than Celf2 WT + MA9 mice, including higher WBCs and lower PLT in PB." (PMID 38514854, 2024). "The results demonstrated that CELF2 was significantly elevated in colorectal, gastric, kidney, leukaemia, liver and melanoma cancers relative to their matched normal tissues." (PMID 34288370, 2021). "Using the criteria of padj < 0.05 and fold-change value > 2, we identified 464 mRNA targets of the CELF2 protein in RIP-Seq and 647 genes that were differentially expressed above the threshold level in RNA-seq of leukemia cells from Celf2 KO + MA9 mice and the control MA9 mice." (PMID 38514854, 2024). "The results revealed that Celf2 KO + MA9 leukemia cells gave rise to more colonies with larger size than MA9 leukemia cells, especially type A colonies, indicating that Celf2 deletion increased the number of LSCs and colony-forming activity, as well as leukemic cell growth potential." (PMID 38514854, 2024). "Deletion of Celf2 significantly enhanced leukemia progression in MA9 mice." (PMID 38514854, 2024). "Thus, our results showed that combined therapy with EPZ-5676 and rapamycin could reduce Celf2 KO + MA9 leukemia burden and prolong the survival time of Celf2 KO + MA9 AML mice by inhibiting both mTORC1 pathway and MLL-fusion target gene expression." (PMID 38514854, 2024). "To dissect the underlying molecular mechanism that drives the enhanced oncogenic potential in Celf2 KO + MA9 cells, we performed global gene expression analysis of leukemia cells from Celf2 KO + MA9 mice and the control MA9 mice by RNA-Seq." (PMID 38514854, 2024). "Notably, combination therapy with a mTORC1 inhibitor (Rapamycin) and a MA9/DOTL1 inhibitor (EPZ-5676) reduced the leukemia burden in MLL-AF9 mice lacking Celf2 in vivo." (PMID 38514854, 2024).
leukemia (continued). "Interestingly, we found that the level of H3K79me, the key downstream symbol of classical pathway of MLL-AF9, was equivalent in Celf2 KO + MA9 and MA9 AML cells, while the mTORC1 signaling pathway was activated only in Celf2 KO + MA9 but not in Celf2 WT + MA9 leukemia cells." (PMID 38514854, 2024).
lung carcinoma (4 papers, 2021 to 2024). "Additionally, CELF2 protein expression is downregulated in tumor tissues as lung cancer and is associated with poor prognosis." (PMID 38791918, 2024). "However, in PrognoScan and Kaplan‐Meier plotter database, we consistently observed that increased CELF2 expression was associated with better prognosis in breast and lung cancer." (PMID 34288370, 2021). "CELF2 has been shown to suppress lung cancer cell proliferation by repressing AKT phosphorylation in a PTEN-dependent manner." (PMID 36230572, 2022). "Analysis using Kaplan‐Meier plotter indicated that elevated CELF2 expression correlated with significantly prolonged survival in both breast and lung cancer." (PMID 34288370, 2021). "Taken together, these results in PrognoScan and Kaplan‐Meier plotter simultaneously illustrated that CELF2 was related to its better survival in breast and lung cancers." (PMID 34288370, 2021). "In this study, we found that elevated CELF2 expression was markedly correlated with prolonged survival in multiple tumours, particularly in breast and lung cancers." (PMID 34288370, 2021). "Interestingly, we found that CELF2 expression was significantly related to a favourable prognosis and a high infiltration abundance of TIICs in breast and lung cancers." (PMID 34288370, 2021). "Notably, there were 24 and 15 cohorts, respectively, that showed high expression of CELF2 as a protective factor in breast and lung cancer." (PMID 34288370, 2021). "Briefly, these findings supported that CELF2 was a potential prognostic biomarker in breast and lung cancers, and might influence TNBC development and metastasis." (PMID 34288370, 2021). "Similarly, there were 24 and 15 cohorts in PrognoScan database, respectively, that showed CELF2 could serve as a predictor of favourable prognosis in breast and lung cancers." (PMID 34288370, 2021).
acute myeloid leukemia (3 papers, 2021 to 2024). Acute myeloid leukemia (AML) is a group of neoplasms arising from precursor cells committed to the myeloid cell-line differentiation. "LncRNA SNHG16 can bind to CELF2 protein and promote CELF2 mRNA degradation, which enhances cellular proliferation and migration of acute myeloid leukemia by regulating PTEN signaling." (PMID 37612724, 2023). "As a key member of RBPs, ELAV-like family protein 2 (CELF2) has been shown to regulate RNA splicing and embryonic hematopoietic development and was frequently seen dysregulated in acute myeloid leukemia (AML)." (PMID 38514854, 2024). "We found that CELF2 deletion occurred in 9.4% of acute myeloid leukemia (AML) patients and the survival time of AML patients with CELF2 deletion was significantly shorter than that of the others." (PMID 38514854, 2024). "In acute lymphoblastic leukemia (ALL) and acute myeloid leukemia (AML) patients and cell lines, the lncRNA small nucleolar RNA host gene 16 (SNHG16) overexpresses, and by lowering CELF2 mRNA stability, this lncRNA enhances proliferation and migration." (PMID 34681716, 2021).
breast tumours (3 papers, 2021 to 2022). "Among the top-ranked differentially expressed genes between these two RNA-seq datasets, CELF2 and NR2F1 were consistently decreased in HR-deleted breast tumors, but upregulated in HR-expressing MDA-MB-231 cells." (PMID 36230572, 2022). "IF staining in matched pairs of HR-deleted breast tumors and matched normal tissue revealed an increase in H3K9 methylation in the tumor, coupled with increased expression of CDK15 and CA9 but decreased expression of CELF2, consistent with the qRT-PCR and RNA-seq results." (PMID 36230572, 2022).
neuroblastoma (3 papers, 2009 to 2016). Neuroblastoma (NB) is the most common solid, extracranial childhood tumor. "CELF2 was identified almost 20 years ago, in multiple studies, first as a CUG repeat binding protein CUG-BP2; in screens for homologs of the Elav family (ETR-3); and as a gene induced in apoptotic neuroblastoma cells (NAPOR)." (PMID 27253061, 2016). "As a RBP, CELF2 (also known as CUGBP2, ETR3, BRUNOL2, Napor2) is a family member of CELF that was identified as a transcript highly expressed in neuroblastoma cells undergoing colchicine-induced apoptosis." (PMID 26314850, 2015).
colorectal cancer (2 papers, 2021 to 2024). A primary or metastatic malignant neoplasm that affects the colon or rectum. "Exosomes from hypoxia colorectal cancer cells transport miR-210-3p to normoxic tumor cells, promoting G1-S cycle transition and proliferation while inhibiting apoptosis by downregulating CELF2 expression." (PMID 34681716, 2021). "The upregulation of CELF2 enhances IR-induced autophagy in colorectal cancer, which has been revealed to be a significant role in this process." (PMID 34681716, 2021). "Additionally, CELF2 has been reported to increase ATG12 levels by modulating mRNA stability, thereby enhancing autophagic flux in colorectal cancer." (PMID 39715205, 2024).
lung squamous cell carcinoma (2 papers, 2021 to 2022). "Further investigation showed CELF2 expression was positively correlated with the infiltration abundance of dendritic cells (DCs), CD8+ T cells and neutrophils in breast invasive carcinoma (BRCA) and DCs in lung squamous cell carcinoma (LUSC)." (PMID 34288370, 2021).
lymph node metastasis (2 papers, 2021 to 2022). "Our results indicated that CELF2 played a protective role in TNBC patients with lymph node metastasis and higher grade, suggesting that CELF2 might affect the prognosis of TNBC patients through lymph node metastasis in these individuals." (PMID 34288370, 2021). "Combined with clinicopathological characteristics, we found that abnormal expression of CELF2 is closely related to tumor size, lymph node metastasis, and distant metastasis, but not to age, gender, CEA, or CA199." (PMID 35941702, 2022). "Notably, CELF2 only impacted the prognosis of triple‐negative breast cancer (TNBC) with lymph node metastasis." (PMID 34288370, 2021).
lymphoma (2 papers, 2021 to 2024). A malignant (clonal) proliferation of B- lymphocytes or T- lymphocytes which involves the lymph nodes, bone marrow and/or extranodal sites. "In contrast, we also found that CELF2 was lower in bladder, brain and central nervous system, breast, head and neck, lung, lymphoma, ovarian, prostate and sarcoma cancers compared with normal tissues." (PMID 34288370, 2021).
myotonic dystrophy (2 papers, 2020 to 2023). An inherited progressive disorder affecting the muscles. "There is strong evidence that CELF2 plays a role in myotonic dystrophy in particular and neurological disease in general." (PMID 33282601, 2020).
myotonic dystrophy type 1 (2 papers, 2020 to 2023). Steinert disease, also known as myotonic dystrophy type 1, is a muscle disease characterized by myotonia and by multiorgan damage that combines various degrees of muscle weakness, arrhythmia and/or cardiac conduction disorders, cataract, endocrine damage, sleep disorders and baldness. "As expected, we were able to pull down proteins known to bind RNA such as CELF2, HNRNPM, and HDLBP, as well as RBPs involved in muscle diseases such as MBNL1, which plays a key role in the pathogenic mechanism of myotonic dystrophy type 1." (PMID 33338663, 2020).
stomach adenocarcinoma (2 papers, 2021 to 2022). "For example, CELF2-associated eRNA targets tumor-suppressor gene CELF2, which is expressed in advanced stage stomach adenocarcinoma (STAD)." (PMID 34439379, 2021).
Alzheimer disease (1 paper, 2020). A progressive, neurodegenerative disease characterized by loss of function and death of nerve cells in several areas of the brain leading to loss of cognitive function such as memory and language. "SNP rs7087063 in gene CELF2 on chromosome 10 was found to be associated with the HMM estimated activity variability during wake (p-value = 3.0×10−8), and we note that CELF2 was previously found to be associated with Alzheimer’s disease." (PMID 33075057, 2020).
cholangiocarcinoma (1 paper, 2021). A carcinoma that arises from the intrahepatic biliary tree (intrahepatic cholangiocarcinoma) or from the junction, or adjacent to the junction, of the right and left hepatic ducts (hilar cholangiocarcinoma). "In contrast, significantly higher expression of CELF2 was only found in cholangiocarcinoma (CHOL), kidney chromophobe (KICH) and kidney renal clear cell carcinoma (KIRC)." (PMID 34288370, 2021).
Cognitive impairment (1 paper, 2026). Abnormal cognition is characterized by deficits in thinking, reasoning, or remembering. "Together, our findings expand the clinical and genetic spectrum of CELF2-related neurodevelopmental disorders and establish a variant-specific mechanism that links CELF2 mislocalization to neuronal hyperactivity, seizures, and cognitive impairment." (PMID 42275152, 2026).
COVID-19 (1 paper, 2022). A disease caused by infection with severe acute respiratory syndrome coronavirus 2. "Of note, we observed numerous DTU genes involved in RNA splicing, with 10 genes (e.g. HNRNPC, SNRPD3, QKI, and LUC7L2) increased major transcript usage and 18 genes (e.g. SNRNP48, NCBP1, CELF2, RALY, and PABPC1) decreased major transcript usage in the COVID-19 patients." (PMID 35421082, 2022).
cystic fibrosis (1 paper, 2016). Autosomal recessive disorder caused by pathogenic variants in the CFTR gene (cystic fibrosis transmembrane conductance regulator), which encodes a chloride and bicarbonate channel expressed in epithelial cells, and follow the diagnosis criteria. "This study demonstrates that there is a significant association between specific variants in CELF2, a gene encoding for a splicing factor involved in controlling the level of exon 9 skipping in CFTR, and risk of developing ARDS in children with pneumonia who do not suffer from cystic fibrosis." (PMID 27596159, 2016).
depression (1 paper, 2022). "Therefore, a decrease in the expression level of hsa-miR-185-5p in AD patients was enhanced by depression and reduced by education, thereby promoting its target CELF2, which reduced the TREM2 function in the microglia and further increased Aβ accumulation." (PMID 36040555, 2022).
diabetes (1 paper, 2025). "Moreover, the HG group presented significantly reduced CELF2 expression, reflecting high glucose-induced downregulation of CELF2 and suggesting its critical role in diabetes-associated erectile dysfunction (ED)." (PMID 40692719, 2025). "The CELF2-related AS events of NECTIN2, DYRK1B, SF1 and FN1 were significantly different and may be potential therapeutic targets for diabetes-related vascular disease." (PMID 40692719, 2025).
Intellectual disability (1 paper, 2026). "We further found that cytoplasmic CELF2 regulated mRNAs critical for synaptic function and neuronal excitability and implicated in epileptic seizures and intellectual disability." (PMID 42275152, 2026).
kidney damage (1 paper, 2023). "Variants in NAT8, and CELF2 were associated with microalbuminuria, MUC1, and rs1077216 with UACR and AS3MT with kidney damage (p < 0.001)." (PMID 37446387, 2023).
lentivirus infection (1 paper, 2025). Virus diseases caused by the Lentivirus genus. "The significant increase in CELF2 mRNA and protein levels following lentivirus infection indicates that CELF2 is a suitable model for studying its effects on HUVECs, particularly in promoting cell proliferation and angiogenesis." (PMID 40692719, 2025).
myeloid leukemia (1 paper, 2024). A clonal proliferation of myeloid cells and their precursors in the bone marrow, peripheral blood, and spleen. "We found that loss of CELF2 promoted myeloid leukemia development by upregulating FAT10-mTORC1 pathway, suggesting a potential tumor suppressing role for CELF2." (PMID 38514854, 2024). "Taken together, these results demonstrated that loss of CELF2 accelerated the myeloid leukemia cell proliferation by activating the FAT10-AKT-mTORC1 signaling pathway." (PMID 38514854, 2024). "Taken together, these results demonstrated that CELF2 loss could significantly accelerate myeloid leukemia growth in vitro and lower the threshold of MLL-AF9-induced AML development in vivo." (PMID 38514854, 2024). "We found that decreased FAT10 expression inhibited the over-growth of CELF2 KD myeloid leukemia cells, reversed the effect of CELF2 deletion." (PMID 38514854, 2024). "In the current study, using hematopoietic-specific Celf2 deletion murine AML models, we observed a strong cooperation between inactivation of Celf2 and MLL-AF9 leading to rapid MA9-induced myeloid leukemia initiation and exacerbated AML progression." (PMID 38514854, 2024). "Our study elucidated a novel mechanism by which the CELF2/FAT10-AKT/mTORC1 axis regulates the proliferation of normal blood cells and the development of AML, thus providing potential therapeutic targets for myeloid leukemia suppression." (PMID 38514854, 2024).
Obesity (1 paper, 2025). Accumulation of substantial excess body fat. "The CELF2 gene is linked to circadian regulation and metabolic characteristics, indicating a common genetic foundation between circadian rhythm and obesity in the human body." (PMID 40024983, 2025).
pneumonia (1 paper, 2016). An acute, acute and chronic, or chronic inflammation focally or diffusely affecting the lung parenchyma, caused by an infection in one or both of the lungs (by bacteria, viruses, fungi, or mycoplasma.). "In summary, multivariable analysis adjusted for the (TG)mTn site in CFTR and for demographic and clinical factors, has identified an association between polymorphisms in CELF2 and risk of developing ARDS in both African American and non-Hispanic Caucasian children with pneumonia." (PMID 27596159, 2016). "The data indicate that SNPs in CELF2 may be associated with the risk of developing ARDS in both African American and non-Hispanic Caucasian children with pneumonia and suggest that the potential role of the splicing factor CELF2 in ARDS should be explored further." (PMID 27596159, 2016).
RASopathy (1 paper, 2017). Developmental syndromes caused by germline mutations (or in rare cases by somatic mosaicism) in genes that alter the Ras subfamily and mitogen-activated protein kinases that control signal transduction. "In addition, two other noteworthy loci (one between KIRREL3 and ETS1, the other between GATA3 and CELF2) overlap between top results from ASD epistasis and RASopathy modifier mapping and contain genes of particular interest." (PMID 28076348, 2017).
schizophrenia (1 paper, 2016). A major psychotic disorder characterized by abnormalities in the perception or expression of reality. "CELF2 is misregulated in a mouse model of spinal muscular atrophy and CELF2 copy-number variation has been linked to schizophrenia." (PMID 27253061, 2016).
thymic hypoplasia (1 paper, 2021). "One DGCR2-located gene, CELF2 (previously called BRUNOL3), is a premRNA alternative splicing factor that is strongly expressed in the developing thymus and has been proposed as a candidate gene for thymic hypoplasia." (PMID 33257998, 2021).
Type I diabetes (1 paper, 2022). "RBFOX binding motifs are found to be co-enriched with MBNL and CELF motifs around the same groups of exons in humans, mice and chickens, and CELF2 and Rbfox2 co-regulate exons in cardiac tissue that show temporal use preferences, or are altered in hearts of a Type I diabetes mouse model." (PMID 34996845, 2022).